DSTNP2 (DSTN pseudogene 2)
Gene: Transcribed unprocessed pseudogene on chromosome 12 (6,884,898 to 6,885,684, forward strand). Ensembl gene ENSG00000248593.
Diseases named in the same sentence as DSTNP2 in open-access papers:
DSTNP2 is named in the same sentence as 2 diseases in open-access papers, as found by Europe PMC text mining. Sharing a sentence is not in itself a finding about the gene and the disease. The quoted sentences say what the papers report.
liver cancer (1 paper, 2021). An epithelial or non-epithelial malignant neoplasm that arises from the liver. "Furthermore, we further verified that the expression of CTD-2510F5.4 and DSTNP2 in liver cancer tissues was higher than that in normal liver tissues by qRT-RCR." (PMID 34426790, 2021).
DSTNP2 also shares sentences with these, for which no sentence is quoted: cancer (1 paper).